HADH (hydroxyacyl-CoA dehydrogenase)
Diseases named in the same sentence as HADH in open-access papers (continued):
Sharing a sentence is not in itself a finding about the gene and the disease.
hyperinsulinemic hypoglycemia (2 papers, 2015 to 2024). An inherited autosomal recessive syndrome characterized by the disorganized formation of new islets in the pancreas and congenital hyperinsulinism. "Mutations in HADH have been linked to hyperinsulinemic hypoglycemia, a condition characterized by abnormalities in insulin secretion and recognized as a fatty acid oxidation deficiency disease." (PMID 38649912, 2024). "We present clinical and laboratory findings together with the long-term clinical course of a case with a deep intronic HADH splicing mutation (c.636+471G>T) causing neonatal-onset hyperinsulinemic hypoglycemia with mild progression." (PMID 26316438, 2015). "Here we present the long-term follow-up of a case with a deep intronic HADH splicing mutation (c.636+471G>T) causing hyperinsulinemic hypoglycemia and review the reported cases so far." (PMID 26316438, 2015).
type 2 diabetes (2 papers, 2019 to 2022). "Another research reveals that HADH expression is different in type 2 diabetic islet β cell dysfunction." (PMID 36035955, 2022). "Although HADH plays an important part in HH, the molecular mechanisms in type 2 diabetes is still unknown currently and remains to be studied." (PMID 31088900, 2019). "Through PPI and GSEA, our study found that DHRS2, ABHD10, HADH and ACLY function together in type 2 diabetes." (PMID 31088900, 2019).
cardiac hypertrophy (1 paper, 2021). "In rats with cardiac hypertrophy caused by left ventricular volume overload, HADH activity was significantly reduced." (PMID 34054926, 2021).
congenital hyperinsulinism (1 paper, 2025). "Because the protein also is a negative regulator of insulin secretion in pancreatic β-cells, inactivating mutations in the SCHAD gene (HADH) cause congenital hyperinsulinism of infancy (CHI) and severe hypoglycemia." (PMID 40474078, 2025).
developmental delay (1 paper, 2021). "HADH mutations were associated with epilepsy and developmental delay." (PMID 34664012, 2021).
familial hyperinsulinemic hypoglycemia type 4 (1 paper, 2010). "Defects in HADH are the cause of familial hyperinsulinemic hypoglycemia type 4." (PMID 21143928, 2010).
ischemia (1 paper, 2015). A hypoperfusion of the BLOOD through an organ or tissue caused by a PATHOLOGIC CONSTRICTION or obstruction of its BLOOD VESSELS, or an absence of BLOOD CIRCULATION. "Surprisingly, activity of HADH and citrate synthase were not affected by ischemia, suggesting that the reduced ATP content was due to dysfunction of mitochondrial complexes rather than loss of mitochondria." (PMID 25889299, 2015).
leptospirosis (1 paper, 2014). A contagious bacterial infection caused by spirochetes of the genus Leptospira. "This is the first report on the detection of leptospiral HADH in the host urine, which may be a possible candidate leptospiral antigen that can be used in the early diagnosis of human and animal leptospirosis." (PMID 24884439, 2014). "HADH was detected in urine before the onset of illness in our hamster model of leptospirosis." (PMID 24884439, 2014).
long chain 3-hydroxyacyl-CoA dehydrogenase deficiency (1 paper, 2024). "Similarly, a possibly damaging missense variant was identified in the gene HADHA, encoding the hydroxyacyl-CoA dehydrogenase, whose recessive gene defect causes pediatric long-chain 3-hydroxyacyl-CoA dehydrogenase deficiency." (PMID 39063061, 2024).
maple syrup urine disease (1 paper, 2025). An autosomal recessive inherited disorder caused by mutations in the BCKDHA, BCKDHB, DBT, and DLD genes. "Of these five, two RGDs (HADH-related disorder and Maple Syrup Urine Disease) were only present in Saraiki ethnic families." (PMID 41516090, 2025).
melanoma (1 paper, 2024). A malignant, usually aggressive tumor composed of atypical, neoplastic melanocytes. "Resistant melanoma cultures rely on fatty acid oxidation and hydroxyacyl-CoA dehydrogenase for their survival upon MAPK treatment." (PMID 38849541, 2024). "Here, we show that inhibition of FA oxidation (by HADH knockdown or etomoxir treatment) efficiently re-sensitized resistant melanoma cells to MAPK therapy, similarly to VARS knockdown." (PMID 38849541, 2024). "VARS depletion affects HADH levels, reduces cellular FA oxidation and re-sensitizes resistant melanoma cells to MAPK therapy." (PMID 38849541, 2024). "HADH protein expression correlated with VARS expression in various melanoma lines: HADH was decreased upon VARS depletion in RES melanoma cells and it was increased upon VARS upregulation in SENS melanoma cells." (PMID 38849541, 2024). "Therefore, we surmised that VARS could promote melanoma resistance at least through regulating HADH mRNA translation and FA oxidation." (PMID 38849541, 2024). "As such, VARS activity protects melanoma from MAPK therapy, at least through promoting HADH translation and FA oxidation cellular activity." (PMID 38849541, 2024). "Our functional esiRNA screen identified five candidate translation targets of VARS (that is, HADH, KIF13B, SLC7A5, QDPR and GOLT1B), whose depletion re-sensitizes resistant melanoma cells to MAPK therapy." (PMID 38849541, 2024). "Among them, VARS regulates the translation of HADH, a valine-enriched protein involved in FA oxidation, whose activity supports adaptation of BRAFV600E melanoma to MAPK therapy." (PMID 38849541, 2024). "HADH expression also correlated with VARS expression in different normal skin and melanoma biopsies." (PMID 38849541, 2024). "Consistent with the role of HADH in FA oxidation, its depletion in two RES melanoma cultures compromised cellular FA oxidation activity and efficiently re-sensitized RES M395 to BRAFi." (PMID 38849541, 2024).
non-alcoholic fatty liver disease (1 paper, 2021). "For example, a decrease in CPT1a expression, coupled with enhanced long-chain acyl-CoA dehydrogenase (LCAD) and HADH mRNAs levels, was detected in liver biopsies from patients with non-alcoholic fatty liver disease." (PMID 34578953, 2021).
prostate carcinoma (1 paper, 2020). A carcinoma that arises from epithelial cells of the prostate gland. "The inferred subset GRN from the PC3 prostate cancer cell line suggests several genes as suppressors of SDHB, such as PNKB, PWP1, PNP, HADH, HTATSF1, and BAZ1B, among which PWP1, HTATSF1, and BAZ1B are transcription regulators." (PMID 33168813, 2020).
renal failure (1 paper, 2014). "The proteins identified in our study, except for leptospiral HADH, are biomarkers known to be involved in renal failure, but are not specific for Leptospira infection." (PMID 24884439, 2014).
schizophrenia (1 paper, 2024). A major psychotic disorder characterized by abnormalities in the perception or expression of reality. "In fatty acid synthesis, DECR1 was upregulated in schizophrenia but downregulated in ketosis, whereas ACACB and HADH were upregulated in both." (PMID 39125835, 2024).
tumor (14 papers, 2017 to 2025). "The cis effect of HADH decreases its protein abundance, causing an accumulation of fatty acids that promotes tumor growth via the PI3K-Akt signaling pathway." (PMID 39762212, 2025). "Moreover, HADH expression was also associated with tumor-infiltrating immune cells (TIICs) in kidney renal clear cell carcinoma." (PMID 36313354, 2022). "Because Akt signaling pathway is involved in tumor progression and invasion, we investigated whether there is a causal relationship between HADH downregulation and increased p-Akt upregulation in MKN45 cells." (PMID 29100311, 2017). "We further constructed xenograft mouse models using HADH-KD and control group cells, and conducted subcutaneous tumor experiments in mice." (PMID 39762212, 2025). "Our comprehensive findings demonstrated that HADH expression was significantly lower in tumor tissues than in normal tissues." (PMID 41583431, 2025). "In summary, we concluded that in AMPAC tumor cells, the downregulation of HADH expression, mediated by cis effect resulting from chromosome 4q loss, disrupted the metabolism of long-chain fatty acids." (PMID 39762212, 2025). "In our data, we observed rapid tumor growth in mice treated with subcutaneous injection of HADH siRNA SNU-478 cells." (PMID 39762212, 2025). "Reduced HADH expression can impede β-oxidation and stimulate fatty acid buildup, which leads to fatty acid metabolism reprogramming and promotes tumor development." (PMID 36313354, 2022). "HADH overexpression may suppress tumor cell proliferation by inhibiting NRF2-mediated glutathione synthesis and inducing oxidative damage in cancer cells." (PMID 41583431, 2025). "We sought to investigate whether HADH downregulation activates the PI3K-Akt signaling pathway in AMPAC tumor cells." (PMID 39762212, 2025). "Spatial transcriptomic analysis confirmed the predominant expression of HADH in tumor cells." (PMID 41583431, 2025). "In conclusion, HADH may be a novel tumor suppressor gene in kidney renal clear cell carcinoma, and its reduced expression is associated with immune cell infiltration and poor prognosis." (PMID 36313354, 2022). "Moreover, our data show that HADH knockdown promotes tumor cell migration and invasion through activation of Akt signaling pathway." (PMID 29100311, 2017). "Our study, on the other hand, supported the idea that HADH was significantly reduced in CRC tissues and was more highly expressed in early tumor tissues." (PMID 41583431, 2025). "IHC staining of tumor and adjacent tissues from 80 CRC patients revealed lower HADH protein expression in tumor tissues." (PMID 41583431, 2025). "Analysis of the GSE39582 dataset revealed notably elevated expression of CCDC34, FBL, and RAB15 in tumor tissues, whereas AQP11 and HADH were notably downregulated." (PMID 41583431, 2025). "To determine the role of Akt activation in tumor migration and invasion, we added the PI3K inhibitor LY294002 to the culture media of MKN45 cells transfected with HADH shRNA in the transwell." (PMID 29100311, 2017). "To validate whether HADH downregulation could promote tumor cell growth, we conducted the cell growth ability assessment on SNU-478-HADH-KD and SNU-869-HADH-KD cells." (PMID 39762212, 2025). "Spatial and single-cell analyses further revealed that within the TME, HADH was predominantly expressed in tumor epithelial cells with low copy number variation rather than in immune or stromal cells." (PMID 41583431, 2025). "It was found that OIP5 silencing in nude-mouse tumor tissues not only slowed tumor growth and reduced size, but also significantly downregulated the expression of fatty acid pathway-related genes (ACSL1, ACSL2, and HADH)." (PMID 36661650, 2022). "The inhibition of the expression of either gene could impair tumor cell proliferation, induce apoptosis, and alter the gene expression level of tryptophan metabolism, indicating that ECHS1- and HADH-driven amino acid metabolism may contribute to tumor development." (PMID 41573739, 2025).
tumor (continued). "In contrast, DPEP1, HADH, PLIN2, SCD5, SLC44A4, and UGT8 may function to suppress tumor growth via the regulation of immune cells with antitumor activity such as resting memory CD4 T cells, resting NK cells, M2 macrophages, resting and activated DCs, and resting mast cells." (PMID 38090559, 2023). "Some adhesion molecules play an important role in tumor recurrence, metastasis, and invasion.(Okegawa, Pong, Li, & Hsieh, 2004) Based on the construction of PPI network and module analysis, ACAA1, ACADSB, ALDH6A1, AUH, HADH,and PCCA with high degree of connectivity were selected as hub genes." (PMID 30793530, 2019).
cancer (11 papers, 2016 to 2025). A tumor composed of atypical neoplastic, often pleomorphic cells that invade other tissues. "Increasing data suggest that HADH is differentially expressed in various types of malignancies and is linked to cancer development and progression." (PMID 36313354, 2022). "Hypermethylation of the HADH gene has been identified as one mechanism underlying its downregulation in CRC, where it modulates cancer cell proliferation through the Wnt/β-catenin and Wnt/ROR2/DVL2 signaling pathways." (PMID 41583431, 2025). "The significance of HADH expression in tumors and its potential mechanisms of action in the onset and progression of certain cancers are summarized in this article." (PMID 36313354, 2022). "Compared to controls, more cancer cells of D-BAT-treated mice had low expression of hydroxyacyl-CoA dehydrogenase (HADHA), the enzyme catalyzing the last three steps of mitochondrial fatty acid (FA) beta-oxidation." (PMID 35835372, 2022). "Furthermore, elevated expression of HADH and ECHS1 has been significantly associated with cancer progression and adverse clinical outcomes across various malignancies, which aligns with the results of this study." (PMID 41573739, 2025). "Functional characteristics and clinical features of HADH in human cancers." (PMID 36313354, 2022). "HADH is involved in fatty acid oxidation and has not been implicated in cancer development." (PMID 27941907, 2016). "It is known that the roles of ACADSB, ACADM, HADH, PYCR1 and ITPKA have been explored in cancers, whereas PAFAH2 not12–16." (PMID 37460577, 2023). "Compared to WT mice, cancer cells of KO mice had no detectable expression of hydroxyacyl-CoA dehydrogenase (HADHA), the enzyme catalyzing the last 3 steps of mitochondrial fatty acid β-oxidation." (PMID 34314388, 2021). "This could be corroborated by our proteomics functional analysis, where we found, for instance, a higher abundance of HADH, PLOD3 and ACAT1 (lysine degradation) and PFKL, NTRK1, PDHB and PDHA1 (central carbon metabolism in cancer) in control piglets compared to UL." (PMID 38409238, 2024).
infection (5 papers, 2014 to 2025). The state of being infected such as from the introduction of a foreign agent such as serum, vaccine, antigenic substance or organism. "This is the first study reporting that leptospiral HADH is released in the urine during the infection." (PMID 24884439, 2014). "We identified a leptospiral protein, 3-hydroxyacyl-CoA dehydrogenase (HADH), which was found to be excreted in the urine of hamsters during the early phase of infection." (PMID 24884439, 2014). "However, several other FAO enzymes, such as ACADL, ACADVL, and HADH, showed high levels in response to infection, which supports increased FAO." (PMID 36453897, 2022). "To explore the roles of HADH and ECHS1 in AML, we downregulated their expressions in MV4-11 and MOLM13 cells via siRNA infection." (PMID 41573739, 2025).
hematological malignancies (1 paper, 2023). "Nevertheless, another FAO enzyme hydroxyacyl-CoA dehydrogenase/3-ketoacyl-CoA thiolase/enoyl-CoA hydratase (HADH) is a prognostic marker in hematological malignancies." (PMID 37256177, 2023).
neurological disorders (1 paper, 2023). "These included genes that encode a component of the SCF ubiquitination complex (FBXO31), an enzyme involved in fatty acid oxidation (HADH) and a member of the KCTD family (KCTD7), mutations in which have been linked to several neurological disorders." (PMID 37818590, 2023).
HADH also shares sentences with these, for which no sentence is quoted: malaria (3 papers); deafness (2); hepatocellular carcinoma (2); Hyperinsulinemia (2); steatosis (2); (SCHAD) deficiency (1); Alzheimer disease (1); endothelial dysfunction (1); epilepsy (1); familial hyperinsulinism (1); glioma (1); Huntington disease (1); leishmaniasis (1); liver cancer (1); malignant lymphoma (1); maturity-onset diabetes of the young (1); metastatic disease (1); metastatic prostate carcinoma (1); morbid obesity (1); myocardial infarction (1); oral carcinomas (1); Parkinson disease (1).